CCNA2 (cyclin A2)
Diseases named in the same sentence as CCNA2 in open-access papers (continued):
Sharing a sentence is not in itself a finding about the gene and the disease.
colorectal cancer (45 papers, 2004 to 2025). A primary or metastatic malignant neoplasm that affects the colon or rectum. "Treatment with Neu5Gc has been shown to promote the proliferation of both colorectal cancer cells and normal intestinal epithelial cells, associated with increased levels of HRAS, CCNA2 (Cyclin A2), and AKT2 proteins." (PMID 40001556, 2025). "Cancer cells, such as colorectal cancer, esophageal carcinoma, and ovarian cancer, can be inhibited from growing and progressing through the cell cycle by the silent CCNA2." (PMID 35601497, 2022). "CCNA2 is overexpressed in several human cancers and closely related to tumor progression and shorter survival in lung, breast, and colorectal cancer." (PMID 34126961, 2021). "For example, in pancreatic ductal adenocarcinoma, overexpression of CDK1 indicates poor prognosis, and CCNA2 is considered a possible biomarker for progression (eg, growth and apoptosis) of colorectal cancer." (PMID 33428596, 2021). "Published literature has reported that CCNA2 functions on various cancers, like colorectal cancer, liver cancer, breast cancer, cervical cancer, and EC." (PMID 32154226, 2020). "The up-regulated CCNA2 expression is found in numerous types of cancer, including pancreatic ductal adenocarcinoma and colorectal cancers." (PMID 32219041, 2020). "FH535 can suppress cell proliferation and migration in colorectal cancer through regulating cyclin A2 and Claudin1." (PMID 32154226, 2020). "In addition, cyclin A (encoded by CCNA2) expression was suppressed when the platelet isoform of phosphofructokinase 1 (PFKP), a key glycolysis enzyme, was knocked down in colorectal cancer cells." (PMID 38794139, 2024). "miR‐424‐5p was shown to promote proliferation and metastasis of colorectal cancer cells by targeting SCN4B and also to inhibit cell proliferation by targeting E2F7, Cyclin E1, Cyclin A2, and Cyclin D1." (PMID 40405535, 2025). "Multiple investigations have documented elevated expression of CCNA2 and CCNB1 in colorectal cancer." (PMID 41614789, 2025). "Via in vitro experiments, CCNA2, CCNB1, and MYC expression was verified in 25 colorectal cancer tissue pairs." (PMID 37504265, 2023). "A previous study reported that the upregulation of cyclin A2 enhanced the migration of hepatocellular carcinoma (HCC), while its downregulation decreased the migration of DLD‐1 and SW620 colorectal cancer cell lines (CRC)." (PMID 35945910, 2022). "CCNA2, MAD2L1, DLGAP5, and RRM2 were all significantly related to the pathological stages of colorectal cancer and were also closely related to the stage of lymph node metastasis." (PMID 33519906, 2020). "The expression of cyclin A2, which is responsible for S phase and G2/M transition, was significantly increased in LPA-treated HaCaT cells, as reported in an LPA-treated colorectal cancer cell line." (PMID 34639115, 2021). "In addition, the results of IF revealed that LETM1 co‐localized with cyclin A2 and CDK2 in colorectal cancer cells." (PMID 33314691, 2021). "Among them, we found that CCNA2, MAD2L1, DLGAP5, and AURKA were related to the overall survival (OS) of colorectal tumors, while RRM2 and AURKA had the relation between disease-free survival (DFS) and colorectal cancer." (PMID 33519906, 2020). "After getting DEGs in tumor tissues compared with normal tissues, network-based analyses (such as protein–protein interaction networks of the DEGs) verified that CCNA2 is a hub gene in LIHC, LUAD, LUSC, STAD, PRAD, HNSC, THCA, medulloblastoma, mantle cell lymphoma, and colorectal cancer." (PMID 35480884, 2022). "Consistently, CCNA2, CCNB1, CCND1, and CCNF have been observed to be upregulated in colorectal cancer, but there is no clear evidence that CCNE1 and CCNJL are also differentially expressed between colon tumor and normal tissues." (PMID 33996604, 2021).
hepatocellular carcinoma (42 papers, 2010 to 2025). A malignant tumor that arises from hepatocytes. "CCNA2 upregulation is also reportedly associated with the progression of other malignancies, including gastric cancer, hepatocellular carcinoma and lung squamous cell carcinoma." (PMID 34253236, 2021). "Over-expressed CCNA2 has been identified in several malignant tissues, such as oral, bladder, and hepatocellular cancer, and may be used as a diagnostic and prognostic biomarker as well as a molecular target for treatment." (PMID 31289358, 2019). "Survival analysis indicated that the expression levels of CCNA2, CHK1, E2F1, and TOP2A are significantly associated with the survival prognosis of hepatocellular carcinoma patients, with p-values of 0.0038, 0.00013, 0.013, and 0.00066, respectively." (PMID 40573296, 2025). "In a study of liver cancer, researchers found that ZHX2 can repress CCNA2 transcription by binding the promoter regions of CCNA2, thereby inhibiting the proliferation of hepatoma cells." (PMID 31956366, 2020). "The modes of action of drug-molecule interactions that may be effective against hepatocellular carcinoma core genes CCNA2, CCNB1, and CDK1 were investigated." (PMID 36479313, 2022). "Ubiquitination of CCNA2 is associated with CDC20; the late promotion complex of ubiquitinated CCNA2 is activated by CDC20, and its overexpression is frequently observed in hepatocellular carcinoma and is a more recognized marker." (PMID 36479313, 2022). "Adopting a series of bioinformatics analysis methods, the current study identified 763 DEGs and seven hub genes (CDC20, CDK1, MAD2L1, BUB1, BUB1B, CCNB1, and CCNA2) that may be involved in hepatocellular carcinoma tumorigenesis and progression." (PMID 33767726, 2021). "It regulates the growth of hepatoma cells through the circ-DB/miR-34a/USP7/cyclin A2 pathway." (PMID 33627631, 2021). "In some recent studies, CCNA2 was suggested to be a prognostic biomarker for liver carcinoma, as it may help in developing an effective therapeutic and/or preventative approach for HCC." (PMID 34659334, 2021). "Here, we identify a hepatocellular carcinoma (HCC) subgroup exhibiting cyclin activation through various mechanisms including hepatitis B virus (HBV) and adeno-associated virus type 2 (AAV2) insertions, enhancer hijacking and recurrent CCNA2 fusions." (PMID 30531861, 2018). "In hepatocellular carcinoma, METTL1/WDR4-mediated m7G tRNA modification significantly promotes the translation of cyclin A2, EGFR, and VEGFA, promoting the spread and metastasis of hepatocellular carcinoma cells." (PMID 39019857, 2024). "In hepatocellular carcinoma cells, GPS1 promotes cell proliferation and migration by upregulating the expression of cyclin A2." (PMID 36520032, 2023). "Numerous studies have indicated CCNA2 and CCNE1 play a central role in various types of malignancy such as hepatocellular carcinoma, breast, and colon cancer." (PMID 35625619, 2022). "In European and a few Japanese hepatocellular carcinoma (HCC) patients, it has been shown that AAV strains similar to AAV2 or AAV13 have the potential to integrate into genes including CCNA2 and CCNE1, contributing to oncogenesis." (PMID 34763675, 2021). "In hepatocellular carcinoma (HCC), METTL1 knockdown suppresses the translation of cyclin A2, leading to the G2/M cell cycle arrest." (PMID 39979979, 2025). "Not surprisingly, among them, CDC20, CCNA2, and BUB1 are all associated with APC-related processes, which may be key nodes in the prognosis and occurrence of hepatocellular carcinoma." (PMID 36479313, 2022). "In addition to CCNA2 regulating cell proliferation by binding with CDC20, CCNA2 is also regulated by CSN1 (signalosome subunit 1) in an ubiquitination-independent manner, which affects the proliferation and migration of hepatocellular carcinoma cells." (PMID 35954210, 2022).
hepatocellular carcinoma (continued). "A possible explanation is a secondary function of ASL, as it has been shown to influence cyclin A2 levels by direct binding in hepatocellular carcinoma, independent of its enzymatic activity within the ASS1-ASL node that also promoted anchorage-independent growth." (PMID 34535676, 2021).
ovarian carcinoma (40 papers, 2011 to 2025). A malignant neoplasm originating from the surface ovarian epithelium. "Particularly, ovarian cancer-associated cell cycle activators, namely cyclin A2 (CCNA2) and aurora kinase A (AURKA), were downregulated by E47, thereby revealing the conserved effects of E47 in ovarian cancer cells." (PMID 35740568, 2022). "Both ovarian carcinoma models showed reductions in Rb phosphorylation and cyclin A2 in tumor tissue at the experimental endpoint (between 44 and 54 days of treatment), sustained up to 16 hours after the final dose was administered." (PMID 38047585, 2024). "CCNA2 protein expression was further confirmed by the HPA database, which suggested that CCNA2 has potential prognostic and therapeutic significance in ovarian cancer." (PMID 34253236, 2021). "We finally determined that CCNA2 that was more highly expressed in ovarian cancer, and an increased CCNA2 RNA expression level was associated with poor PPS in all patients with ovarian cancer." (PMID 34253236, 2021). "In addition, the overexpression of CCNA2 can enhance the reproduction, metastasis, and invasive ability of cancer cells and is closely connected to the occurrence and deterioration of ovarian cancer, liver cancer, and esophageal squamous cell carcinoma (ESCC)." (PMID 34787756, 2022). "Besides cell migration, ectopic overexpression of ERβ1 also inhibited proliferation of ovarian cancer cells which was accompanied by induced p21, a cyclin-dependent kinase inhibitor, and reduced cyclin A2 mRNA expressions." (PMID 28859612, 2017). "Finally, we identified CCNA2 as the hub gene that is crucial for ovarian cancer progression." (PMID 34253236, 2021). "CCNA2 is overexpressed in metastatic breast, lung, and bladder cancers, while CCNB1 contributes to metastasis in cervical, breast, and ovarian cancers." (PMID 41244050, 2025). "The protein expression levels of CCNA2, CCNB1, CDC20, CDCA8, CDK1, KIF11 and TOP2A were high in ovarian cancer tissues, which was further confirmed via the HPA database." (PMID 34253236, 2021). "For RFS of patients with ovarian cancer, SPOCK2 and FAXDC2 were unfavorable prognostic biomarkers but ADAMDEC1, CCNA2, FAM181A, FOXA2, LRRTM1, NEIL3 and XPR1 were favorable prognostic biomarkers." (PMID 31794425, 2019). "Using real-time PCR, we found that silencing SMYD3 significantly decreased the mRNA levels of CCNA2, CCNB2, CCND2, CDK1 and CDK2 (p<0.05) but increased the mRNA levels of WEE1 (p<0.05), suggesting an essential role for SMYD3 in ovarian carcinoma proliferation." (PMID 31417652, 2019). "Role of NEK2, CCNA2, and AURKA as potential targets in ovarian cancer has been recently highlighted by a detailed systematic bioinformatic study." (PMID 26992853, 2016). "For example, CCNA2 mRNA levels were found to be decreased significantly with fold change -1.07, -4.33, -1.06, and -4.17 when treated with romidepsin, SNAO32, dauricine, and doxorubicin in A549, primary ovarian cancer, BxPC3, and MCF7 cell lines, respectively." (PMID 36203433, 2022). "Finally, we identified CCNA2 and BUB1B as candidate hub genes for ovarian cancer progression, as their high expression was correlated with tumor stage and overall survival of ovarian cancer." (PMID 34253236, 2021). "Although not as important as the other A-type cyclin (cyclin A2/cyclin A), cyclin A1 also is involved with the development of taxane resistance in ovarian cancer." (PMID 33182737, 2020). "This investigation highlighted CCNA2, TRIP13, CDK1, CDC20 and PRC1 as viable targets for our structure-based drug discovery campaign, as they all had a crystallised structure available in the Protein Data Bank, strong evidence of a role in ovarian cancer and known inhibitors." (PMID 39184376, 2024).
ovarian carcinoma (continued). "Cyclin A2/E1 activation in HCC and BRCA1 inactivation in breast and ovarian cancers may thus converge towards a similar rearrangement signature, with specificities reflecting the different ways by which these genetic alterations induce replication stress or modulate response to it." (PMID 30531861, 2018).
colon carcinoma (37 papers, 2009 to 2024). "In mice, CCNA2 deficiency increased DNA damage in colon mucosal epithelial cells, caused inflammation and increased cell proliferation and developmental abnormalities that increased colon cancer incidence." (PMID 37504265, 2023). "For example, the abnormal expression of CCND1 and CCNE1 promotes the proliferation of lung adenocarcinoma, the down-regulation of cyclin A2 affects the proliferation of colon cancer cells; however, cyclin A2 is highly expressed in thyroid cancer." (PMID 34908101, 2022). "Meanwhile, some studies have shown that CCNA2 can be used for the early detection and prognosis of colon cancer." (PMID 35906548, 2022). "In this study, we identified six cyclin genes (CCNA2, CCNB1, CCND1, CCNE1, CCNF, and CCNJL) that are potential diagnostic biomarkers of colon cancer." (PMID 33996604, 2021). "Among the four datasets of colon cancer from The Cancer Genome Atlas and the Gene Expression Omnibus, six cyclin genes (CCNA2, CCNB1, CCND1, CCNE1, CCNF, and CCNJL) were differentially expressed between normal and tumor tissues." (PMID 33996604, 2021). "For example, the expression of NPTX1 is down-regulated in colon cancer and inhibits cell proliferation via the down-regulation of Cyclin A2 and cyclin-dependent kinase 2 (CDK2) expression." (PMID 31113871, 2019). "A total of 27 anticolon cancer targets of THCQF were selected, among which four genes (CCNB1, CCNA2, IL1A, and MMP3) were shown to effectively predict patient outcomes in a prognostic colon cancer model." (PMID 35479514, 2022). "Given the potential of the four important cyclin genes (CCNA2, CCNB1, CCNE1, and CCNF), we further investigated the genes co-expressed with them in colon cancer via WGCNA." (PMID 33996604, 2021). "In our study, we found that NPTX1 inhibits cell proliferation by inducing cell cycle arrest and down-regulating cycle-related proteins (Cyclin A2 and CDK2), these findings are consistent with findings in colon cancer." (PMID 31113871, 2019). "The expression of cyclin A2, CDK1 and CDK2 in colon cancer HT-29 cells was decreased upon the knockdown of ANO1." (PMID 27732935, 2016). "In another study, NPTX1 could inhibit cell proliferation through down-regulating cyclin A2 and CDK2 expression in colon cancer." (PMID 38012562, 2023). "Overall, patients with lower expression of the four genes (CCNA2, CCNB1, CCNE1, and CCNF) had worse survival outcomes, which implies that these members of the cyclin family might be ideal prognostic biomarkers for colon cancer." (PMID 33996604, 2021). "However, it seems that the significance of CCNA2 and CCNE1 for the prognosis of colon cancer hasn’t been elucidated yet." (PMID 33996604, 2021). "Moreover, it was shown that cyclin A2 negatively controls cell motility by promoting RhoA-ROCK activation through a direct interaction with RhoA in breast and colon cancer cells." (PMID 26418031, 2015). "Analysis of dataset GSE29623, an mRNA and microRNA profile in colon cancer, supported that miR-622 positively correlated with signature genes in cell cycle pathway, such as CDC6 (r = 0.421), CDK2 (r = 0.336), CCNE1 (r = 0.423), CCNA2 (r = 0.412), CCNA5 (r = 0.350), and MCM10 (r = 0.423)." (PMID 38166756, 2024). "In fact, the expression level of E2F2 was very low level in colon cancer and E2F2 inhibition could enhance proliferation and cell cycle of colon cancer cells by suppressing the expression of surviving and regulating the expression of C-MYC, CCNA2, MCM4 as well as CDK2." (PMID 32117628, 2020).
glioma (37 papers, 2010 to 2025). A benign or malignant brain and spinal cord tumor that arises from glial cells (astrocytes, oligodendrocytes, ependymal cells). "Cyclin A2 has also been studied in the context of glioma, and its overexpression was associated with poor prognosis in GBM patients." (PMID 38971772, 2024). "A literature research on these genes revealed that all of them have been associated with glioma by different bioinformatic analyses, and CCNA2 has been recently proposed as an immunologic biomarker for GBM." (PMID 39286768, 2024). "CCNA2 is related to the cell cycle and has been suggested as a possible molecular marker in low-grade gliomas, and plays a regulatory role in the development of various kinds of cancer." (PMID 40884870, 2025). "In light of bioinformatic studies highlighting the close association between ORC6 and key oncogenic genes, including Cyclin A2, Cyclin B2, and TOP2A in GBM, our study explored the potential role of ORC6 in regulating their expression in glioma cells." (PMID 38971772, 2024). "Another KIF20A co-expressed gene, CCNA2, its overexpression in glioma results in a significant cell proliferation rate and activate G2M checkpoint pathways." (PMID 39624268, 2024). "We have analyzed the level of Reg-2 and its newly identified targets that encode the cyclins CCND1, CCNE1, CCNE2, CCNB1, CCNA2, and the kinases PLK1 and AURKA in glioma tumors." (PMID 38238463, 2024). "To further validate the role of CCNA2 in glioma, we assessed if changes in CCNA2 expression affect glioma cell proliferation and malignant abilities." (PMID 35903107, 2022). "CCNA2 has been little studied in glioma, and its mechanism of action in glioma needs to be further investigated." (PMID 35774141, 2022). "We assessed the protein levels of cdc25A, CDK2, and Cyclin A2 and found that the levels of these three proteins were reduced in glioma cells treated with PTE." (PMID 33737656, 2021). "Therefore, CCNA2 may be a potential diagnostic marker and an important drug target for glioma." (PMID 30995921, 2019). "The clinical data verified the association of the identified genes (i.e., KIF2C, CCNA2, NDC80, KIF11, KIF23, ANLN, and CENPM) with the targeted therapy response and prognosis of glioma patients." (PMID 31682596, 2019). "The identified DryNB included seven genes (KIF2C, CCNA2, NDC80, KIF11, KIF23, ANLN and CENPM) that were significantly associated with drug sensitivity or resistance of glioma patients to the targeted therapies." (PMID 31682596, 2019). "Treatment with MNF also sensitized C6 glioma tumor xenograft to growth arrest via the downregulation of Galnt3 and other cell cycle regulators, such as Ccna2, Cdkn3, and Bub1b." (PMID 25505565, 2013). "In this study, five prognosis-related differentially expressed immune-related genes (PR-DE-IRGs) (CCNA2, HMGB2, CASP3, APOBEC3C, and BMP2) highly associated with glioma were identified for a prognostic model through weighted gene co-expression network analysis, univariate Cox and lasso regression." (PMID 35601497, 2022). "Furthermore, we demonstrated that CCNA2 promotes glioma proliferation, migration, and invasion and regulates macrophage polarization." (PMID 35903107, 2022). "Moreover, the animal experiment suggested that CCNA2 knockdown suppressed glioma growth in vivo, while CCNA2 overexpression promoted tumor growth." (PMID 35903107, 2022). "Flow cytometry data showed that the knockdown of SIPA1 in A172 cells arrested cell cycle progression in the G1 phase, which was further supported by the downregulation of cell cycle proteins Cyclin A2, Cyclin D1 and Cyclin E1 in glioma cells with SIPA1 knockdown." (PMID 35431649, 2022). "In summary, PLK1, CCNA2, CCNB2, and AURKA were screened as candidate diagnostic marker genes of glioma, and hsa-let-7b-5p could inhibit the invasion and metastasis of glioma cells." (PMID 30995921, 2019).